IL6 (interleukin 6)
Diseases named in the same sentence as IL6 in open-access papers (continued):
Sharing a sentence is not in itself a finding about the gene and the disease.
graft versus host disease (20 papers, 2016 to 2025). An immune system disorder that occurs after allogeneic hematopoietic stem cell transplant and is a reaction of donor immune cells against host tissues. "IL-6 is involved in acute and chronic inflammation and is important in the pathophysiology of graft-versus-host disease (GVHD) and BA." (PMID 37928553, 2023). "Another pentacyclic triterpenoid such as ursolic acid (UA) has shown anti-inflammatory activity in activated T cells, B cells and macrophages, and against graft-versus-host disease in vivo mouse model, significantly reducing serum levels of pro-inflammatory cytokines IL-6 and IFN-γ." (PMID 34360922, 2021). "Using different cytokines, such as IL-6, IL-13, or LPS, it could generate BM-MDSCs in vitro and successfully treated diseases in vivo, like graft-versus-host disease, skin transplantation and pancreatic islet transplantation." (PMID 33250891, 2020). "Inhibition of IL-6-initiated signaling through the downstream JAK/STAT pathway has emerged as a possible strategy to prevent and treat graft-versus-host disease (GVHD)." (PMID 35566660, 2022). "We also found that IL-1β, IL-2, IL-6 and IL-8 were significantly increased in episodes in which multiple viruses were simultaneously detected, and samples positive for EBV DNA and graft-versus-host disease had a further increase of IL-1β and IL-8." (PMID 36014102, 2022). "However, excessive and unregulated production of IL-6 result in a number of chronic immune disorders, including a role in the chronic inflammation seen in transplant rejection, patients on dialysis, in crescentic glomerulonephritis, and graft versus host disease (GVHD)." (PMID 28127571, 2017). "CAR-NK cells are safer than CAR-T cell therapy since they release neither IL-1 nor IL-6 and seldom induce graft-versus-host disease (GVHD)." (PMID 39948620, 2025). "Enhanced Treg production following IUT, particularly of CD62L+ CD25+ FOXP3+ Tregs, protects against graft-v-host disease, and together with putative Breg (expressing IL10, IL5, IL6, FOXP3, TGF-β), probably influenced the resulting tolerogenic or immunogenic responses." (PMID 37226255, 2023). "Notably, NK cells exhibit low graft versus host disease (GvHD) potential and rarely induce significant toxicities due to limited persistence in the body, lack of T-cell receptors, decreased CRS especially IL-6, and safety of allogenic NK cells, making them a promising platform for CAR engineering." (PMID 38694508, 2024).
Hashimoto thyroiditis (20 papers, 2014 to 2025). An autoimmune disorder caused by the production of autoantibodies against thyroid tissue. "Another IL-6 gene promoter (−572 C/G) polymorphism has been described to be a specific genetic marker for susceptibility to Hashimoto’s thyroiditis." (PMID 40565595, 2025). "The allele C in IL6-174 G/C is also associated with Hashimoto's thyroiditis, however, only retained significance after multiple testing correction in the log-additive model (OR = 1.28, CI = 1.06–1.54, p-value = 8.9×10−3)." (PMID 25127106, 2014). "In clinical studies, XYSJW has demonstrated a significant ability to reduce the levels of IFN-γ, IL-2, and IL-6 while increasing IL-10 levels in patients with Hashimoto’s thyroiditis and chronic lymphocytic thyroiditis, thereby regulating the Th1/Th2 balance." (PMID 40584613, 2025). "Chronic inflammation is also present in Hashimoto’s thyroiditis, an autoimmune thyroid disorder characterized by tissue damage, fibrosis, and the release of inflammatory cytokines including Interleukin 6 (IL-6), Tumor Necrosis Factor-alpha (TNF-α), and Interleukin 1 beta (IL-1β)." (PMID 40218202, 2025). "One pathway is through a common inflammatory pathway involving factors such as interleukin-6 (IL-6), IL‐12, IL‐10 and tumor necrosis factor that were shown to be significantly higher in women with autoimmune hypothyroidism and euthyroid TAI+ women compared to TAI− controls." (PMID 39888679, 2025). "Interestingly, high circulating levels of IL6 have been also reported in Hashimoto’s thyroiditis where they positively correlate with the number of Th22 lymphocytes, which in turn is related to the TPOAbs titre." (PMID 35181847, 2022). "In addition, this variation affected IL-6 level in patients with Hashimoto thyroiditis in a Turkish population." (PMID 33177541, 2020). "In one study, levels of serum interleukin‐6 (IL‐6), tumor necrosis factor‐α, IL‐12, IL‐10, and IR (HOMA‐index) were investigated in women with Hashimoto’s disease, in euthyroid women with TAI and a control group." (PMID 35195084, 2022). "Inflammatory cytokines including IL-6, TNF-α and IFN-β have been found extensively in both thyroids and sera of patients with Hashimoto’s thyroiditis." (PMID 33304319, 2020). "According to a study carried out in Italy, individuals who suffer from both Hashimoto’s thyroiditis and CKD have elevated levels of specific inflammatory markers, including C-reactive protein (CRP) and interleukin-6 (IL-6), when compared to those who only have CKD." (PMID 39004740, 2024). "In Hashimoto’s thyroiditis, the immune response of Th1 lymphocytes predominates, which, together with macrophages, produce mainly pro-inflammatory cytokines, including INF-γ, TNF-α, IL-1, and IL-6." (PMID 37371976, 2023). "In this study, IL-17, IL-1β and IL-6 levels were found to be markedly increased in the TG-immunized rats exposed to DBP, suggesting that Th17 and pro-inflammatory cytokines play an important role in DBP exacerbation of chronic lymphocytic thyroiditis." (PMID 29133889, 2017). "The concentrations of IL-8, 10, IL-1B, and TNF-α were significant higher in patients with Hashimoto’s disease (p < 0.05), whereas the concentrations of IL-6 and 12 were non-significant among patients with Hashimoto’s disease as compared to healthy controls (p > 0.05)." (PMID 37241088, 2023). "Cytometric Bead Array (CBA) analysis of pro and anti-inflammatory cytokines (IFN-gamma, IL-2, IL-6, IL-17 A, TNF-alpha and IL-4, IL-10) was done in 15 PTC irrespective of Lymphocytic Thyroiditis (LT) and 16 Hashimoto’s Thyroiditis (HT) cases." (PMID 37563607, 2023). "This is due to the observed negative correlation between serum IL-6 levels and FT4 levels in individuals diagnosed with autoimmune hypothyroidism." (PMID 38317717, 2023).
Hashimoto thyroiditis (continued). "We determined that patients with Hashimoto’s thyroiditis had substantial levels of IL-1B, IL-8, and IL-12 and TNF-α, but that the levels of IL-6 and IL-12 were non-significant compared to the healthy control group." (PMID 37241088, 2023).
helminth infection (20 papers, 2010 to 2025). "This experiment led to the conclusion that in vivo IL-6 limits the Th2 response by modification of Treg-cell phenotype and promotes host susceptibility following helminth infection." (PMID 26044883, 2015). "In this study, while IL-6 and IL-8 were very high in all the subgroups at baseline, increased TNFα levels were associated with helminth infection (either egg positivity at baseline or with high Ascaris-specific IgE profile in antigen-stimulated assays)." (PMID 25209883, 2014). "Our results revealed that IL-6 determines susceptibility to helminth infection by modifying the phenotype of the Treg-cell population and limiting protective Th2 responsiveness." (PMID 24185641, 2014). "In order to assess the impact of IL-6 deficiency on Treg-cell function in vivo following helminth infection, we performed Foxp3 staining in concert with intracellular cytokine staining at a time-point when effector cell responses were dysregulated in IL-6−/− mice (day 7)." (PMID 24185641, 2014). "This may even extend to mediators such as IL-9, which is not only upregulated in helminth infection, but more intensely so in IL-6-deficient mice." (PMID 24185641, 2014). "Thus, in vivo, IL-6 limits the Th2 response, modifies the Treg-cell phenotype, and promotes host susceptibility following helminth infection." (PMID 24185641, 2014). "The resistant phenotype of the IL-6-deficient mouse could be fully reversed by administration of an anti-IL-2:IL-2 complex, rescuing the Treg-cell phenotype, inhibiting Ag-specific Th2 responses, and restoring susceptibility to chronic helminth infection." (PMID 24185641, 2014). "Intestinal tissue damage due to helminth infections will also increase the secretion of IL-10 and IL-6." (PMID 41239264, 2025). "Studies have shown that IL-6 expression is critical during the acute phase of helminth infections in mice, enhancing IgA secretion in the gastrointestinal mucosa and inducing fever during inflammation." (PMID 38786064, 2024). "Also, IL-6, a pleiotropic cytokine with pro- or anti-inflammatory properties, when deficient in mice has been found to result in worm expulsion with stronger Th2 responses, indicating that the IL-6 may promote host susceptibility against helminth infection by limiting Th2 response." (PMID 33639942, 2021). "New insights into the role of IL-6 in helminth infections have recently been reported by Smith and Maizels (2014)." (PMID 26044883, 2015). "The IL-6-independent generation of Th17-cell responses to helminth infections raised the question of the functional contribution of these cells to helminth immunity." (PMID 24185641, 2014). "polygyrus infection of IL-6−/− mice, there was a significant outgrowth of Th17 cells to levels similar to those in infected BALB/c mice, reflecting a greater fold increase of Th17 cells in IL-6-deficient than in sufficient mice following helminth infection." (PMID 24185641, 2014). "The group without evidence of helminth infection (egg-IgElo) had the lowest or undetectable levels of all pro-inflammatory (IL-6, IL8 and TNFα) median values in response to HIV-p24 and Ascaris-stimulation." (PMID 25209883, 2014). "Early stimulation of Treg-cell populations in the absence of IL-6 was crucial in regulating excessive pro-inflammatory responses and preventing resistance to helminth infection." (PMID 24185641, 2014). "As IL-6 signaling is also important for Th2- but not Th1-cell differentiation, we cannot exclude a function of Tec in the IL-6 sensing during Th2 differentiation, with an impact on other Th2-driven diseases such as worm infections." (PMID 35003062, 2021). "Since the MyD88-mediated pathway plays a key role in IL-1R signaling, unimpaired IL-1β–induced TNF-α and IL-6 production by macrophages from helminth-infected host suggests that the effect of the helminth infection is not on MyD88-dependent signals, but is likely to be on the TRAM/TRIF pathway." (PMID 25010669, 2014).
helminth infection (continued). "Cytokine ELISA data showed that helminth infection significantly inhibited LPS-, but not IL-1β-, induced TNF-α and IL-6 production, suggesting that helminth infection specifically inhibits the TLR4 signaling pathway." (PMID 25010669, 2014). "A Th2 immune response is desirable in helminth infection, but as the ileum is not the site of infection, it was surprising to observe the up-regulation of genes, including CD86, Ovar-DRB1, IL1RL1 and IL-6, that polarize the immune response towards a Th2 response." (PMID 35576023, 2022).
Hypercalcemia (20 papers, 2012 to 2025). An abnormally increased calcium concentration in the blood. "Similarly, hypercalcemia has been linked to heightened inflammatory states, including elevations in C-reactive protein and interleukin-6 levels." (PMID 41153752, 2025). "Additionally, it has been documented that blocking osteoclastic bone resorption with a neutralizing antibody against human IL-6 restored hypercalcemia linked to cancer cells." (PMID 38993553, 2024). "G-CSF and IL-6 are implicated in mild and severe hypercalcemia, respectively." (PMID 37041610, 2023). "Moreover, hypercalcemia has been associated with cosecretion of PTHrP and IL-6." (PMID 27316348, 2016). "Hypercalcemia, observed in 80% of cases, was primarily cytokine-driven, involving IL-6, RANKL, MIP-1α, and TNF-α." (PMID 40438858, 2025). "Cytokine-mediated hypercalcemia (~60%), primarily driven by IL-6, RANKL, MIP-1α, and TNF-α, was most frequent, followed by PTHrP-mediated hypercalcemia (~25%) and less commonly by 1,25-dihydroxyvitamin D dysregulation (~15%)." (PMID 40438858, 2025). "This is supported by the observation that Chinese hamster ovarian cells overexpressing both IL-6 and PTHrP, in contrast to those with IL-6 overexpression alone, had marked hypercalcemia." (PMID 29056680, 2017). "Hypercalcemia induced by RWGT2 is lowered in tumor-bearing mice following administration of IL-6 neutralizing antibodies." (PMID 29056680, 2017). "The MET-1/NOD/SCID model demonstrated that RANKL expression correlates with the secretion of PTHrP and IL-6, as well as with hypercalcemia." (PMID 23198151, 2012). "Previous studies report that hypercalcemia in the C26 model is mediated by IL-6 and PTHrP." (PMID 31600911, 2019). "Three of them were considered to develop humoral hypercalcemia (high PTHrP level), whereas one patient resembling normal PTHrP was believed to have hypercalcemia related with tumor synthesis of osteoclast-activating factors [interleukin (IL)-1, IL-6, tumor necrosis factor-α, and prostaglandins]." (PMID 28443817, 2017). "Additionally, they present with hypercalcemia and thromboembolic vascular symptoms due to the high production of parathyroid hormone and stimulation of stanniocalcin-1 signaling mediated by interleukin-6 (IL-6)." (PMID 36123851, 2022). "In one series of 21 patients, 11 had PTHrP-mediated hypercalcaemia, while two patients had raised TNF-α and IL-6." (PMID 26082799, 2015). "In ATL patients with metastasis and hypercalcemia, activation of the MIP-1α, TNF-α, IL-1, and IL-6 molecules is induced by Tax-stimulated NF-κB activation." (PMID 23198151, 2012). "Increased circulating IL-6 has been reported in hypercalcemic and normocalcemic patients and does not correlate with the severity of hypercalcemia." (PMID 29056680, 2017). "Additionally, proinflammatory cytokines, especially interleukin-6, may independently promote osteoclast activation and bone resorption, contributing to hypercalcemia without elevated vitamin D metabolites." (PMID 41179272, 2025).
intervertebral disc degeneration (20 papers, 2015 to 2025). "Furthermore, higher levels of cytokines like TNF, IL-6 and IL-8 are linked to painful degenerative disk disease and can cause the infiltration of host immune cells as well as increased sensitization of nerve fibers upon AF and cartilage endplate ruptures." (PMID 39192354, 2024). "Furthermore, IL-6 inhibition may be effective for lower back pain caused by intervertebral disc degeneration and pain associated with CASPR2 antibody-related autoimmune encephalitis." (PMID 40538700, 2025). "Both TNF-α and IL-6 are well-established pro-inflammatory cytokines known to take part in the pathology of intervertebral disc degeneration." (PMID 40095903, 2025). "IL-6 and its receptor were aberrantly expressed in injured cartilage tissues of patients with intervertebral disc degeneration, and miR-10a-5p suppressed IL-6 expression and inhibited IL-6 mediated cartilage cell oxidative stress and ferroptosis." (PMID 35549778, 2022). "Previous studies also have shown that IL-6 was significantly increased in intervertebral disc degeneration tissues and positively correlated with the degree of intervertebral disc degeneration and symptom severity." (PMID 35096205, 2022). "Number of studies supported the relationship between intervertebral disc degeneration and IL1, IL6 gene variants." (PMID 35964023, 2022). "Patients were divided into the low- and high-score groups by the cumulative grade of intervertebral disc degeneration, and the cut-off value was 18 according to the levels of IL-6 and TNF-α." (PMID 35096205, 2022). "Intervertebral disc degeneration is related to varieties of proinflammatory cytokines IL-1 β, IL-6, and TNF-α and their metabolites." (PMID 34676010, 2021). "Interleukin 6 and cathepsin B seem to be related with physiopathology of intervertebral disc degeneration, since the levels of both were higher in discs of patients with intervertebral disc degeneration." (PMID 31482941, 2019). "They suggest that when intervertebral disc degeneration occurs, PLA2 is activated by various proinflammatory mediators, such as interleukin-1, tumor necrosis factor-α, and interleukin-6, which are secreted by the degenerative intervertebral disc." (PMID 36498718, 2022). "Fifteen days after the induction of intervertebral disc degeneration, significant changes were observed, such as reduction in the expression metalloprotease-9 (MMP9) and interleukins (IL-6 and IL-10)." (PMID 26997908, 2016). "One postulated mechanism is that when intervertebral disk degeneration occurs, PLA2 is activated by various proinflammatory mediators such as interleukin-1, tumor necrosis factor-α, and interleukin-6, which are secreted by the degenerative intervertebral disk." (PMID 25879590, 2015). "And in this study, we observed inconsistent trends in IL-6 and TNF-α after surgery, which may indicate that TNF-α plays a more critical role in intervertebral disc degeneration." (PMID 35096205, 2022). "Previous studies have shown that intervertebral disc degeneration is a complex process of multi-factor interaction, in which a variety of cytokines are involved in the pathological progression of IVDD, e.g. IL-1β, TNF-α, IL-6." (PMID 34483910, 2021). "Data confirm that interleukin 6 and cathepsin B are possible related to the physiopathology of intervertebral disc degeneration, however they do not represent a biomarker in serum." (PMID 31482941, 2019).
Kaposi's sarcoma (20 papers, 2007 to 2025). A malignant neoplasm characterized by a vascular proliferation which usually contains blunt endothelial cells. "In Kaposi’s sarcoma infected with Kaposi’s-sarcoma-associated herpesvirus, the viral IL-6 is differentially N-glycosylated compared to the host IL-6, which contributes to enhanced activation of JAK/STAT signaling and B-cell proliferation." (PMID 35563790, 2022). "Another example is Kaposi sarcoma-associated herpes virus-encoded interleukin-6 (vIL-6) that has two potential N-glycosylation sites (Asn78 and Asn89)." (PMID 26029999, 2015). "Regardless, the importance of studying TGF-β induction by HIV-1 Vpr is also stressed by the fact that increased TGF-β signaling can lead to pathologic concentrations of IL6 and the development of Kaposi sarcoma." (PMID 40632811, 2025). "Dependence on cytokines, such as basic fibroblast growth factor, oncostatin M and interleukin 6, has been shown for the growth of Kaposi’s sarcoma-derived cells in vitro." (PMID 35267506, 2022). "Kaposi’s sarcoma cells released IL-6, IL-8, Ccl5, and Cxcl10 in response to long-term poly(I:C) exposure." (PMID 35737804, 2022). "The pro-inflammatory cytokine IL-6 is secreted by Kaposi’s sarcoma cells in response to 24 hours’ exposure to poly(I:C)." (PMID 35737804, 2022). "Correlation between NF-κB and IL-6 was also reported in the case of Kaposi’s sarcoma herpesvirus infection." (PMID 35458402, 2022). "Third, corticosteroid stimulation of KS development can also occur through upregulation of oncostatin M and IL-6/sIL-6R and blockade of transforming growth factor-β, an autocrine inhibitory factor for Kaposi's sarcoma." (PMID 28736762, 2017). "In the IRIS patient that presented with Kaposi's sarcoma, increases in IL-6, IL-10, IL-12, IL-13 and IFN-γ expression were shown." (PMID 20929543, 2010). "Such blockade of NF-IL-6 by PD-98059 inducing the inhibition of IL-6 levels was shown in Kaposi sarcoma cells." (PMID 19068145, 2008).